ZPBP2 (zona pellucida binding protein 2)
Description:
Is implicated in sperm-oocyte interaction during fertilization.
Synonyms: ZPBPL; MGC41930
Tractability: Antibody: UniProt places it where antibodies can reach, with high confidence; UniProt predicts a signal peptide or a membrane-spanning region; its Gene Ontology location is reachable by antibodies, with medium confidence.
Gene: Protein-coding gene on chromosome 17 (39,868,202 to 39,877,896, forward strand). Ensembl gene ENSG00000186075.
Subcellular location: Cytoplasmic vesicle, secretory vesicle, acrosome; Secreted
Gene Ontology:
Biological process: acrosome assembly; binding of sperm to zona pellucida
Cellular component: nucleus; acrosomal vesicle; zona pellucida receptor complex; cell body; extracellular region
Genetic constraint (gnomAD): Loss-of-function variants: 28 observed, 31.27 expected, observed/expected ratio (o/e) 0.9, 90% interval 0.66 to 1.23. The upper end of that interval is the gene's LOEUF score, 1.23, which puts it in group 5 of 6, group 1 being the genes least tolerant of losing a copy. Missense variants: 323 observed, 346.46 expected, observed/expected ratio (o/e) 0.93, 90% interval 0.85 to 1.02. Synonymous variants: 115 observed, 117.39 expected, observed/expected ratio (o/e) 0.98, 90% interval 0.84 to 1.14.
Homologues: Orthologues: chimpanzee ZPBP2 (98% identical), macaque ZPBP2 (93% identical), rabbit ZPBP2 (83% identical), pig ZPBP2 (79% identical), dog ZPBP2 (78% identical), guinea pig ZPBP2 (72% identical), mouse Zpbp2 (70% identical), rat Zpbp2 (68% identical). Paralogues in human: ZPBP (34% identical).
Diseases named in the same sentence as ZPBP2 in open-access papers:
ZPBP2 is named in the same sentence as 22 diseases in open-access papers, as found by Europe PMC text mining. Sharing a sentence is not in itself a finding about the gene and the disease. The quoted sentences say what the papers report.
asthma (35 papers, 2011 to 2025). "Additional evidence from human studies stems from a meta‐analysis of GWAS studies of asthma in a Puerto Rican population, which revealed a significant association between SNPs in the region encompassing ZPBP2 and asthma." (PMID 40133993, 2025). "The GSDMB variant (rs2305479-T) was part of the same credible set as the asthma-linked ZPBP2 missense variant rs11557467-T with high LD (r = 95%) and lower posterior probability (1.5% for GSDMB vs 4.0% for ZPBP2)." (PMID 36653354, 2023). "In a meta-analysis of GWAS in Puerto Ricans, the only region associated with asthma was the ZPBP2 locus and the current genotypic dataset was analyzed as a part of the data." (PMID 31063461, 2019). "The already presented SNP rs12936231 has been reported as a high-risk allele for asthma and autoimmune diseases and suggested to cause chromatin remodeling and alter transcription of certain genes, including ZPBP2, GSDMB, and ORMDL3." (PMID 31362752, 2019). "The ZPBP2 region from chromosome 17q21 has been consistently replicated as an asthma-susceptibility locus across diverse ethnic groups including Puerto Ricans and this region regulates its gene expression in Puerto Ricans." (PMID 31063461, 2019). "Specific to asthma, differential expression at the ZPBP2/GSDMB/ORMDL3 locus was identified resulting from allele-specific chromatin remodeling mediated by CTCF." (PMID 29228930, 2017). "We confirmed in CD4+ and CD8+ T cells that CTCF binding was almost completely lost in the ZPBP2 intronic region from subjects carrying the asthma-risk SNP, and this finding was true at the allele-specific level." (PMID 27848966, 2016). "The second CTCF-binding motif was altered by asthma-risk SNP (rs12936231) in the ZPBP2 intronic region causing a G-to-C change in the CTCF motif, which was predicted in our in silico analysis and previously shown to impair CTCF binding." (PMID 27848966, 2016). "The extended chromosome 17 locus has also been implicated previously as containing SNPs associated with asthma spanning three main genes; ZPBP2/GSDMB/ORMDL3 and it is still unclear which genes/polymorphisms underlie these associations." (PMID 24066901, 2013). "The A-allele is part of the asthma-associated haplotype HapA and is associated with lower expression level of ZPBP2 in CEU LCLs." (PMID 22271045, 2012). "In conclusion, the asthma-associated HapA haplotype variants of the ZPBP2 promoter region and the putative promoter for the minor ORMDL3 isoform had higher in vitro promoter activity compared to the variants associated with the HapB haplotype." (PMID 22271045, 2012). "The rs4795397-A allele that boosts the ZPBP2 promoter activity in vitro is also part of the asthma-associated haplotype HapA." (PMID 22271045, 2012). "We found that a single nucleotide polymorphism rs4795397 influences the activity of ZPBP2 promoter in vitro in an allele-dependent fashion, and also leads to nucleosome repositioning on the asthma-associated allele." (PMID 22271045, 2012). "The gene encoding the zona pellucida-binding protein 2 (ZPBP2) has been revealed as a common locus of both childhood and adulthood asthma by several studies, supported by the association of several intronic SNPs as well as variants located within the intergenic region of ZPBP2 and GSDMB." (PMID 30805318, 2019). "Our recent studies found interaction between 17q12-q21 alleles, DNA methylation levels, sex, and asthma with genetic association being more pronounced in males and DNA methylation of the ZPBP2 promoter region being associated with reduced risk of asthma in females." (PMID 31560728, 2019). "Thus, the asthma-risk haploblock harbours linked SNPs that switch the binding site of CTCF from the ZPBP2 to the ORMDL3 intronic region." (PMID 27848966, 2016).
asthma (continued). "The asthma-associated region 17q12-q21 harbors three genes, the zona pellucida binding protein 2 (ZPBP2), gasdermin B (GSDMB) and ORM1-like 3 (ORMDL3), that show allele-specific differences in expression levels in lymphoblastoid cell lines (LCLs) and CD4+ T cells." (PMID 22271045, 2012). "Therefore, it is conceivable that spermatozoa from male carriers of the asthma-associated rs4795397-A allele have a higher supply of the ZPBP2 protein and potentially an increased fertilization capacity." (PMID 22271045, 2012). "The ZPBP2 promoter was highly methylated in cell lines homozygous for the asthma-associated HapA haplotype (n = 5) and in heterozygous cell lines (n = 6), but had lower methylation levels in cell lines that were homozygous for the non-asthma associated HapB haplotype (n = 5)." (PMID 22271045, 2012). "Mutations in these genes, including ORMDL3, GSDMB, ZPBP2, and IKZF3, result in reduced protein folding in the endoplasmic reticulum leading to an overall pro-inflammatory effect in asthma patients." (PMID 39237910, 2024). "In the STEPS study, asthma risk alleles in IKZF3, GSDMA, GSDMB, ZPBP2, and ORMDL3 genes were associated with a higher risk of a wheezing illness (all P values ≤.02)." (PMID 36967681, 2023). "Asthma risk alleles in GSDMA, GSDMB, IKZF3, ZPBP2, and ORMDL3 genes were associated with wheezing illnesses in early childhood, especially rhinovirus-positive wheezing illnesses." (PMID 36967681, 2023). "Both ZPBP2 and GRID2IP are part of loci that have been previously associated with autoimmune disease, including asthma and inflammatory bowel diseases (IBDs)." (PMID 35814780, 2022). "In fact, early studies had revealed that SNPs associated with asthma co-regulate the expression of ORMDL3, GSDMB, and ZPBP2 in Latinos." (PMID 30805318, 2019). "Several lines of evidence suggest that the human ZPBP2 region harbors an enhancer and a CTCF-binding site whose functions are modified by genetic variants associated with predisposition to asthma and several other chronic inflammatory diseases." (PMID 31560728, 2019). "Our previous work demonstrated that lower methylation levels of certain CGs in the ZPBP2 and GSDMA promoters in peripheral blood cells are associated with asthma in females." (PMID 28241063, 2017). "We found strong associations between childhood asthma and variants near gasdermin B (GSDMB) and zona pellucida‐binding protein 2 (ZPBP2) on chromosome 17q21.1 (e.g., rs4795399‐T, odds ratio = 1.43, p value = 1.61E−23), which is consistent with previous studies." (PMID 40133993, 2025). "Like ZPBP2 that was identified in our GWAS of children's own genotypes and childhood asthma, GSDMB also lies within the same core region on 17q12‐q21 that is strongly linked to childhood‐onset asthma." (PMID 40133993, 2025). "The strong link between ZPBP2 and asthma has also been demonstrated in murine models." (PMID 40133993, 2025). "Hypermethylated GATA3 (location 10p14), a significant regulator of Th2 differentiation, is associated with reduced asthma risk in cord blood, while ZPBP2 (Zona Pellucida Binding Protein 2) hypomethylation results in asthma in a lymphoblastoid cell line at genetic location 17q12-q21." (PMID 34566492, 2021). "This genomic region consists of a number of genes, including ORMDL3, GSDMB, IKZF3, ZPBP2, and GSDMA that are in LD and may either be individually or jointly responsible for the asthma association." (PMID 30541564, 2018). "ZPBP2 has a well-known role in fertilisation and male fertility, and it has been proposed that this gene may play a role in influencing the prevalence of asthma in the population." (PMID 24044605, 2013). "To validate whether ORMDL3 is a risk factor for adult-onset asthma, we sought to replicate the association of polymorphisms in ORMDL3, GSDMB, ZPBP2 and IKZF3 and asthma in an adult Chinese Han population." (PMID 21985515, 2011).
asthma (continued). "Currently, there is extensive research on asthma susceptibility genes, confirming associations with genes such as interleukin-4 (IL-4), interleukin-13 (IL-13), β2 adrenergic receptor (ADRB2), Zona Pellucida Binding Protein 2 (ZPBP2), and numerous other candidate genes." (PMID 40433469, 2025). "We found that CISDs associate with the 17q21 locus (GSDMB/ZPBP2) as well as TSLP, IL33, and the gene encoding the IL33 receptor, IL1RL, which all have previously shown to be associated with asthma, and have also shown to be functionally relevant in asthma models." (PMID 36653354, 2023). "Al-though the Zona pellucida-binding protein 2 is described as being implicated in sperm–oocyte interaction during fertilization, the lower expression of this gene in peripheral blood cells is associated with a reduced risk of asthma in females but not males." (PMID 33572894, 2021). "Two SNPs in ZPBP2 and ORMDL3 (rs12936231 and rs4065275, respectively) that were previously shown to be functionally relevant to asthma, were also in high-LD with the four SNPs that we identified in the VDR-binding regions of the 17q12-21.1 loci." (PMID 38567749, 2024). "These same four SNPs in 17q12-21.1 were also in high-LD with two SNPs in ZPBP2 and ORMDL3 (rs12936231 and rs4065275, respectively) that were previously shown to be functionally relevant to asthma." (PMID 38567749, 2024). "Although the direction of the sex- and age-specific methylation differences in ZPBP2 is opposite to that of IFNγ, both our and the Naumova studies highlight the significance of age and sex in DNA methylation that may modify genetic effects in diseases like asthma." (PMID 24891923, 2014). "Hence, methylation levels of ZPBP2 exon 1 influence ZPBP2 RNA levels and explain the apparent contradiction between high in vitro activity and FAIRE enrichment of the ZPBP2 promoter region and lower expression of ZPBP2 in LCLs that carry the asthma-associated haplotype HapA." (PMID 22271045, 2012). "It is important to note, however, that while the current experimental evidence excludes IKZF3 (IKZF3 is not affected by the haplotype effect in LCLs or T lymphocytes), it is not sufficient for ruling out ZPBP2, GSDMB or GSDMA as contributors to predisposition to asthma." (PMID 22271045, 2012).
childhood asthma (2 papers, 2023 to 2025). "Previous studies have reported that the 17q21 locus alleles in genes GSDMA, GSDMB, IKZF3, ZPBP2, and ORMDL3 are associated with increased risk and severity of childhood asthma and increased number of early wheezing illnesses." (PMID 36967681, 2023).
Primary Biliary Cirrhosis (2 papers, 2015). "ZPBP2 encodes a protein paralogue of the zona pellucida binding protein and harbors a missense SNP associated with primary biliary cirrhosis." (PMID 26484354, 2015).
adult onset asthma (1 paper, 2011). "In this study, we aimed to evaluate the association of polymorphisms in ORMDL3, GSDMB, ZPBP2 and IKZF3 and adult-onset asthma in a Chinese Han population." (PMID 21985515, 2011).
autoimmune conditions (1 paper, 2020). "Some studies in the pediatric population also postulate that genes such as zona pellucida binding protein 2 (ZPBP2) and pyrin and HIN domain-containing protein 1 (PYHIN1) are responsible for the relationship between pediatric IBD and autoimmune conditions, including pulmonary diseases." (PMID 32181078, 2020).
Infertility (1 paper, 2025). "Disruption of either ZPBP1 or ZPBP2 has been linked to infertility due to abnormal sperm morphology and function." (PMID 40276155, 2025).
systemic lupus erythematosus (1 paper, 2017). An autoimmune multi-organ disease typically associated with vasculopathy and autoantibody production. "This study aimed to assess the association between 14 single nucleotide polymorphisms (SNPs) in six genes (IRF8, TMEM39A, IKZF3, ORMDL3, GSDMB, and ZPBP2) and systemic lupus erythematosus (SLE) in a Chinese Han population sample." (PMID 28427360, 2017).
Turner syndrome (1 paper, 2018). Turner syndrome is a chromosomal disorder associated with the complete or partial absence of an X chromosome. "The striking differences in methylation between Turner syndrome patients with one and three copies of Xq suggest that at least one X-linked modifier of ZPBP2 methylation levels resides on the q-arm of the X chromosome." (PMID 29463315, 2018). "Our findings are consistent with hypomethylation of the ZPBP2 promoter region in the blood cells of Turner syndrome patients compared to 46,XX females." (PMID 29463315, 2018). "In the DNA samples from Turner syndrome patients that carried only one X, the ZPBP2 DMR methylation levels were lower than in individuals who carried two or more copies of intact X chromosomes, or the Xq arms." (PMID 29463315, 2018). "To identify the X-linked genes responsible for the levels of DNA methylation at the ZPBP2 locus, we compared methylation in fibroblast cell lines from Turner syndrome patients with karyotypes 45,X and 46,X,i(Xq), females with trisomy X, as well as females with deletions within the Xq arm." (PMID 29463315, 2018). "ZPBP2 methylation levels in these cell lines were higher than in 45,X Turner syndrome patients." (PMID 29463315, 2018).
ZPBP2 also shares sentences with these, for which no sentence is quoted: autoimmune disease (5 papers); cancer (2); Crohn disease (2); Globozoospermia (2); inflammatory bowel disease (2); male infertility (2); acute lymphoblastic leukemia (1); allergic rhinitis (1); emphysema (1); meningioma (1); Obesity (1); pulmonary diseases (1); rheumatoid arthritis (1); ulcerative colitis (1).